TLR4 (toll like receptor 4)
Diseases named in the same sentence as TLR4 in open-access papers (continued):
Sharing a sentence is not in itself a finding about the gene and the disease.
mastitis (continued). "Studies revealed that the TLR4 gene is upregulated in mastitis tissue in comparison with normal tissue." (PMID 38520296, 2024). "The objective of our study was to analyse 89 missense SNPs belonging to six genes (CXCR2, CXCL8, TLR4, BRCA1, LTF, BOLA-DRB3), which were found to be associated with genetic resistance or susceptibility to mastitis." (PMID 37174521, 2023). "We have analysed the missense SNPs belonging to six genes (CXCR2, CXCL8, TLR4, BRCA1, LTF, BOLA-DRB3) and identified one marker (rs110124025) in BOLA-DRB3 that was associated with frequency of mastitis and with the number of affected quarters." (PMID 37174521, 2023). "Increased TLR4 levels were detected in the colon and mammary gland of AN mice, accompanied by enhanced downstream NF-κB and NLRP3 pathways, which are involved in mastitis pathogenesis and other gut dysbiosis-associated diseases." (PMID 37069691, 2023). "Increased LPS and systemic inflammation subsequently disrupt the blood-milk barrier and facilitate the development of mastitis through TLR4-NF-κB/NLRP3 signatures." (PMID 37069691, 2023). "RMT from mastitis cows (M-RMT) to recipient mice transferred mastitis symptoms through the LPS-mediated TLR4-cGAS-STING-NF-κB/NLRP3 pathways." (PMID 36451232, 2022). "MiR-125b and miR-146a aggravate and alleviate mastitis in dairy cows by targeting the NF-κB inhibitor-interacting Ras-like 2 (NKIRAS2) and Toll-like receptor 4 (TLR4)/tumor necrosis factor receptor-associated factor 6 (TRAF6)/NF-κB pathways, respectively." (PMID 35681895, 2022). "Previous studies have shown that alpinetin, cepharanie, curcumin, astragalin and thymol can release mastitis level via reducing TLR4, IκBα, NF-ΚB, P65, ERK and MAPK expression." (PMID 36672605, 2022). "In the liver of cows with E. coli-induced mastitis, demethylation of toll-like receptor 4 (TLR4) gene was observed." (PMID 36336691, 2022). "Ruminal microbiota transplantation from mastitis cows (M-RMT) to mice induced mastitis symptoms in recipient mice along with increased mammary proinflammatory signature activation of the TLR4-cGAS-STING-NF-κB/NLRP3 pathways." (PMID 36451232, 2022). "This study established that LPS-induced EMT was mediated by the TLR4/NF-κB/Snail signaling pathway, suggesting potential roles of Snail in goat mastitis." (PMID 34944199, 2021). "Retinoic acid, a derivative of vitamin A attenuates inflammatory response in LPS-induced rat mastitis model by suppressing the TLR-4/NF- κB signalling pathway." (PMID 33509059, 2021). "We observed that the expression of TLR2 was double the expression of TLR4 in both neutrophils and macrophages during mastitis, which reflects the role of TLR2 in mediating an effective immune response against S. aureus." (PMID 34235202, 2021). "In the in vivo detection of the expression of TLR4/NF-κB/Snail, we found that the critical members of this signaling pathway were upregulated in all the mastitis glands." (PMID 34944199, 2021). "The mRNA and protein expression of TLR4, NF-κB, IL-1β, and TNF-α were up-regulated in mastitis induced by LPS and activated the TLR4/NF-κB signaling pathway." (PMID 34692813, 2021). "This demonstrates that MNK has an anti-inflammatory effect in the LPS-induced mastitis model by inhibiting the TLR4-NF-κB signaling pathway." (PMID 35174140, 2021). "Particularly during E. coli mastitis, TLR4 activation by LPS and subsequent production of specific eicosanoids responsible for endothelial barrier impairment was documented." (PMID 34073753, 2021). "The lipopolysaccharide of Gram-negative bacteria is always recognized by host cell receptors (such as TLR-4), which is one of the induced factors of pathogenesis for mastitis." (PMID 34222051, 2021). "This study provides evidence that LPS induces EMT in GMECs through the TLR4/NF-κB/Snail signaling pathway and lays a theoretical foundation for further exploration of the pathological mechanism and treatment of mastitis." (PMID 34944199, 2021).
mastitis (continued). "In this work, we explored the roles of TLR2 and TLR4 in S. uberis infections in TLR2−/− and TLR4−/− mice to further understand the molecular defense mechanism in S. uberis mastitis." (PMID 32098158, 2020). "It is striking that melatonin similarly suppressed TLR4 and NF- κ B in mice infected with LPS and provided protection against mastitis." (PMID 32223750, 2020). "Studies show that TLR4 is the main pattern recognition receptor in response to E. coli-induced mastitis in mice, goats and dairy cows." (PMID 32823867, 2020). "To explore the mechanism of berberine hydrochloride in attenuating LPS-induced murine mastitis, we selected TLR4 and NF-κB, two classical signal transduction pathways to examine." (PMID 29849710, 2018). "It is thus clear that indirubin treatment of lipopolysaccharide induced mastitis in a mouse model and activity in mouse mammary epithelial cells via bated TLR4 and its two main Myd88-dependent pathways, NF-κB and MAPK." (PMID 28255203, 2017). "In E. coli-induced mastitis udders, the mRNA levels of TLR4 and CD36 were upregulated during the infection." (PMID 26976286, 2016). "In in vivo studies evaluating E. coli-induced mastitis, dairy animals showed signs of acute clinical mastitis, including somatic cell counts, decreased milk yield, udder swelling and TLR4 mRNA upregulation during the early stages of infection." (PMID 26976286, 2016). "In conclusion, the present study showed differential gene expression of the TLR4/ NF-κB signaling pathway in the mammary tissue of Chinese Holstein cattle with mastitis." (PMID 25706977, 2015). "In conclusion, our study provides new evidence for better understanding the differential expression and mechanisms of the TLR4 /NF-κB signaling pathway in Chinese Holstein cattle with mastitis." (PMID 25706977, 2015). "The involvement of TLR signaling (particularly TLR2 and TLR4) in the host response to mastitis is well-documented; however, less is known about the involvement of the NLR and RIG-I pathways." (PMID 24470219, 2014). "Recently, the Toll-Like Receptor (TLR)-4 transduction pathway was suggested as a crucial contributor to robust mammary gland immune defence against E. coli mastitis." (PMID 21352611, 2011). "In this study, as well as in others, TLR2 and TLR4 are characterized as being significantly influenced by E. coli mastitis." (PMID 21352611, 2011). "However, GSDMD−/− mice exhibited less severe tissue damag during mastitis, with reduced immune cell infiltration and more intact alveolar structures than in TLR4−/− mice." (PMID 40552401, 2025). "Additionally, elevated succinate exacerbates gut dysbiosis and stimulates the production of microbial extracellular vehicles containing LPS, thereby aggravating mastitis through TLR4 activation." (PMID 41139776, 2025). "Among TLRs, TLR2 and TLR4 are particularly important in bacterial induced mastitis." (PMID 39199398, 2024). "Moreover, inhibiting TLR4 signaling attenuated inflammation in the mammary gland and protected mammary tissues in an LPS-induced murine mastitis model, suggesting that effectively modulating TLR4 signaling is crucial for treating mastitis." (PMID 39609525, 2024). "Similarly, rosmarinic acid and nuciferine alleviate LPS-induced mastitis by inhibiting the TLR4/MyD88/NF-κB signaling pathway and production of TNF-α, IL-1β, and IL-6 in MMECs." (PMID 39199398, 2024). "Additionally, the review discusses various bioactive compounds and probiotics that have been identified as potential therapeutic agents for preventing and treating mastitis by targeting TLR2/TLR4/NF-κB signaling pathway." (PMID 39199398, 2024). "In a LPS-induced mouse model of mastitis, geniposide (2.5, 5, and 10 mg/kg in vivo; 25, 50, and 100 μg/mL in vitro) has been demonstrated to alleviate inflammatory response by the inhibition of TLR4." (PMID 37333874, 2023). "Additionally, Alpinetin was shown to have a marked antiinflammatory effect in LPS‐induced mastitis by blocking the TLR4/IκB‐α/NF‐κB pathway." (PMID 36627822, 2023).
mastitis (continued). "Supplementing mice with the Neu inhibitor zanamivir alleviated recurrent LPS exposure-induced mastitis, which supports that diminished TLR4-mediated inflammation could be attributed to blocking host Neu." (PMID 36451232, 2022). "In the present study, genes NOD2, CXCL8, OAS2, and TLR4 were differentially expressed in the blood transcriptome of subclinical mastitis cows and involved in the NOD-like receptor, Toll-like receptor pathway and were identified as key candidates for this study." (PMID 36204322, 2022). "CXCL8 is an important neutrophil chelator in BME cells, induces chemotaxis in the target cells, and has a significant change in expression levels upon TLR4 activation, which could serve as a potential biological for improving the outcome of mastitis markers." (PMID 36204322, 2022). "Finally, we found that the expression of key molecules of the TLR4/NF-κB/Snail signaling pathway was increased in mastitis tissues." (PMID 34944199, 2021). "Higher expression of TLR2 and TLR4 in neutrophil during mastitis might indicate higher recognition and elevated immune response against the microbes." (PMID 34235202, 2021). "The results of Western blot analysis revealed that ATC could suppress the expression of toll-like receptor 4, phosphorylation of extracellular signal-regulated kinase, and activity of c-Jun N-terminal kinase in the LPS-stimulated mastitis model." (PMID 33281536, 2020). "Activation of TLR4-dependent signaling may recruit inflammatory cells and promote the process of mastitis during E. coli infection." (PMID 32823867, 2020). "The temporal sequences of SYK, PTK2B, TLR4, and IL-1β expression are similar, suggesting that there might be an immune response pathway in bMECs participating in bovine mastitis inflammatory response." (PMID 31447828, 2019). "The present study demonstrates that berberine hydrochloride exerts anti-inflammatory effects by inhibiting inflammatory cell infiltration, the production of TNF-α, IL-1β, and IL-6, and the activation of the TLR4/NF-κB signaling pathway in a mouse model of mastitis." (PMID 29849710, 2018). "Indirubin improved LPS-induced mouse mastitis by suppressing TLR4 and downstream NF-κB and MAPK pathway inflammatory signals and might be a potential treatment of mastitis and other inflammatory diseases." (PMID 28255203, 2017). "The results indicated that E. coli-induced mastitis could trigger TLR4 and CD36 mRNA expression and activate the downstream signaling pathways in Xinong Saanen dairy goats." (PMID 26976286, 2016). "Moreover, mastitis-related hypomethylation of the TLR4 promoter had also been found in these samples." (PMID 27439381, 2016). "Additionally, this study indicates that CD36 plays a vital role in the LPS-induced activation of downstream signaling cascades and mediates E. coli phagocytosis via TLR4 in pGMECs, which offers a novel treatment strategy for mastitis." (PMID 26976286, 2016). "While, TLR4 protein expression was increased in mastitis tissue." (PMID 25706977, 2015). "Taken together, these data suggest that the immune response of Chinese Holstein cattle with mastitis may occur by a MyD88-dependent channel that is mediated by TLR4/ NF-κB." (PMID 25706977, 2015). "Thus, it is suggested that NFκB activation via LPS/TLR4 signaling in alveolar epithelial cells weakens the alveolar TJs with claudin compositional changes in mastitis." (PMID 23626786, 2013). "We found that DBD can effectively control inflammation and oxidative stress in E. coli-induced mastitis mice by regulating the TLR4/NF-κB and Nrf2/HO-1 signaling pathways, suggesting that DBD may be a very effective new method for the treatment of bovine mastitis." (PMID 40266913, 2025). "The association of the TLR4 gene polymorphism with somatic cell count/score (SCC/SCS) may be attributed to the high genetic correlation between SCS and the occurrence of clinical mastitis." (PMID 38520296, 2024).
mastitis (continued). "Associations between genotypes (mainly SNPs) and mastitis-associated phenotypes (mainly SCS) have been demonstrated for 157 candidate genes in ruminants, several of which have been reported in multiple independent association studies (e.g., CXCL8, CXCR1, TLR4)." (PMID 36759924, 2023). "The cell membrane receptor TLR4 recognizes exogenous stimuli such as lipopolysaccharide from E. coli, and the signal is transmitted through MyD88, activates NF-κB, and then modulates many of the pro-inflammatory cytokines and chemokine transcripts that contribute to the development of mastitis." (PMID 35893774, 2022). "Discovery of TLR4/SYK axis may provide a new target for drug research on mastitis." (PMID 36672605, 2022). "Furthermore, SYK was down-regulated in peripheral blood neutrophils of dairy cows with mastitis (E. coli), participates in the TLR4 cascade, regulates the production of reactive oxygen species (ROS) in bovine neutrophils and affects neutrophils to kill pathogens." (PMID 36672605, 2022). "Based on significantly increased TLR4, IκB, TNF-α, IL-1β protein expressions, and NF-κB nuclear protein expression induced by E. coli, we inferred that it activated TLR4/NF-κB signaling pathways in bMECs and macrophages, consistent with E. coli causing mastitis through the TLR4/NF-κB pathway." (PMID 32733409, 2020). "Therefore, the oxidative stress of sows around parturition may also facilitate TLR4 activation by exogenous pathogens and partly contribute to the high prevalence of peripartum mastitis." (PMID 27938408, 2016). "Therefore, TLR4 may be a strong candidate for functional studies to enhance mastitis resistance in cattle." (PMID 19508288, 2009). "In the context of mastitis, a prevalent inflammatory disorder of the mammary gland, the activation of toll-like receptors (TLRs), particularly TLR2 and TLR4, triggers the production of pro-inflammatory cytokines via the NF-κB signaling pathway." (PMID 40871398, 2025). "Levels of IFN-γ, IL-4, TNF-α, MYD88, CCL5, TLR4, TLR9, LTF, PRLR, Keap1 and OXSR1 genes expression were significantly up-regulated in ewes affected with mastitis than resistant ones." (PMID 40542007, 2025). "Mastitis-affected ewes had considerably higher levels of IFN-γ, IL-4, TNF-α, MYD88, CCL5, TLR4, TLR9, LTF, and PRLR gene expression than resistant ones." (PMID 40542007, 2025). "Some of the genes differentially regulated during mastitis have been reported in multiple independent expression studies (e.g., CXCL8, CXCR1, LTF, TLR4)." (PMID 36759924, 2023). "LPS was found to cause inflammation in mouse mammary glands by upregulating mRNA expression of the CD14/TLR4/NF-κB/MAPK pathway, while dexamethasone and ATF reduced LPS-induced mastitis in mice by downregulating mRNA expression of this pathway." (PMID 36090098, 2022). "Exposure to LPS has been reported to induce mtDNA synthesis through Toll-like receptor (TLR)-4, which is also involved in the activation of the NF-κB and NLRP3 pathways and mastitis pathogenesis." (PMID 36451232, 2022). "Immunofluorescence colocalization data showed that TLR4 and SYK had a high correlation in bovine mastitis mammary gland tissue and bMCEs." (PMID 36672605, 2022). "The data also showed that SYK gene expression and protein levels have a strong consistency in bovine mastitis, and NLRP3, TLR4 and IL-1β as well." (PMID 36672605, 2022). "Proteins like complement C4 (C4), BRCA1, TLR4, MBLA, and calcium voltage-gated channel auxiliary subunit alpha2delta 1 (CACNA2D1) are reported potential biomarkers in mastitis which were also found in our study." (PMID 34222390, 2021). "The research on mastitis development reported that the inflammatory factors including IL-6, IL-8, TNF-ɑ, and TLR4 are consistently altered." (PMID 35173767, 2021). "The mRNA expression of genes responsible for the inflammatory response (TLR4, LBP, IL-1β, IL-6, IL-8, NF-κB and TNF-α) was significantly increased, consistent with the results of exogenous LPS-induced mastitis by infusion." (PMID 26893357, 2016).